GRM2 (glutamate metabotropic receptor 2)
Description:
Dimeric G protein-coupled receptor which is activated by the excitatory neurotransmitter L-glutamate. Plays critical roles in modulating synaptic transmission and neuronal excitability. Upon activation by glutamate, inhibits presynaptic calcium channels, reducing further glutamate release and dampening excitatory signaling (By similarity). Mechanistically, ligand binding causes a conformation change that triggers signaling via guanine nucleotide-binding proteins (G proteins) and modulates the activity of down-stream effectors, such as adenylate cyclase. May mediate suppression of neurotransmission or may be involved in synaptogenesis or synaptic stabilization. (Microbial infection) Plays an important role in influenza virus internalization. (Microbial infection) Acts as a host entry factor for rabies virus that hijacks the endocytosis of GRM2 to enter cells. (Microbial infection) Acts as a host entry factor for SARS-CoV-2 that hijacks the endocytosis of GRM2 to enter cells.
Synonyms: mGluR2; GPRC1B; mGlu2; GLUR2
Tractability: Small molecule: a drug acting on it is in phase 2 or 3 trials; a structure with a bound ligand is known; a high-quality ligand is known; it belongs to a druggable protein family. Antibody: its Gene Ontology location is reachable by antibodies, with high confidence; UniProt places it where antibodies can reach, with medium confidence; UniProt predicts a signal peptide or a membrane-spanning region. PROTAC: its protein half-life has been measured; a small molecule that binds it is known.
Target class: Family C G protein-coupled receptor; Metabotropic glutamate receptor; Small molecule receptor (family C GPCR); Membrane receptor; Neurotransmitter receptor (family C GPCR)
Chemical probes: BI-4737 (high quality)
Gene: Protein-coding gene on chromosome 3 (51,707,061 to 51,718,616, forward strand). Ensembl gene ENSG00000164082.
Subcellular location: Cell membrane; Synapse; Cell projection, dendrite
Pathways (Reactome):
Signal Transduction: Class C/3 (Metabotropic glutamate/pheromone receptors); G alpha (i) signalling events
Gene Ontology:
Molecular function: glutamate receptor activity; protein binding; G protein-coupled receptor activity; group II metabotropic glutamate receptor activity; scaffold protein binding; calcium channel regulator activity
Biological process: G protein-coupled glutamate receptor signaling pathway; chemical synaptic transmission; negative regulation of adenylate cyclase activity; positive regulation of phosphatidylinositol 3-kinase/protein kinase B signal transduction; regulation of synaptic transmission, glutamatergic; adenylate cyclase-inhibiting G protein-coupled glutamate receptor signaling pathway; behavioral response to nicotine; G protein-coupled receptor signaling pathway; glutamate receptor signaling pathway; glutamate secretion; presynaptic modulation of chemical synaptic transmission; regulation of dopamine secretion; regulation of glutamate secretion; regulation of response to drug; response to cocaine
Cellular component: plasma membrane; astrocyte projection; axon; dendrite; glutamatergic synapse; membrane; neuron projection; postsynaptic membrane; presynaptic membrane; synapse
Genetic constraint (gnomAD): Loss-of-function variants: 32 observed, 57.33 expected, observed/expected ratio (o/e) 0.56, 90% interval 0.42 to 0.75. The upper end of that interval is the gene's LOEUF score, 0.75, which puts it in group 3 of 6, group 1 being the genes least tolerant of losing a copy. Missense variants: 916 observed, 1,224.3 expected, observed/expected ratio (o/e) 0.75, 90% interval 0.71 to 0.79. Synonymous variants: 435 observed, 496.4 expected, observed/expected ratio (o/e) 0.88, 90% interval 0.81 to 0.95.
Homologues: Orthologues: chimpanzee GRM2 (99% identical), macaque GRM2 (99% identical), rabbit GRM2 (99% identical), dog GRM2 (98% identical), pig GRM2 (98% identical), rat Grm2 (98% identical), guinea pig GRM2 (98% identical), mouse Grm2 (97% identical), tropical clawed frog grm2 (74% identical), zebrafish grm2a (72% identical), zebrafish grm2b (71% identical), Drosophila melanogaster mtt (44% identical), and 2 more. Paralogues in human: GRM3 (68% identical), GRM4 (46% identical), GRM6 (45% identical), GRM8 (45% identical), GRM5 (44% identical), GRM7 (44% identical), GRM1 (44% identical).
Diseases named in the same sentence as GRM2 in open-access papers:
GRM2 is named in the same sentence as 87 diseases in open-access papers, as found by Europe PMC text mining. Sharing a sentence is not in itself a finding about the gene and the disease. The quoted sentences say what the papers report.
schizophrenia (74 papers, 2008 to 2025). A major psychotic disorder characterized by abnormalities in the perception or expression of reality. "Consistent with mRNA expression levels, none of the permissive or repressive GRM2-associated HPTMs was altered in schizophrenia DLPFC samples." (PMID 38396013, 2024). "The co-morbidity of schizophrenia and SCRD may in part stem from dysfunction in common brain mechanisms, which include the glutamate system, and in particular, the group II metabotropic glutamate receptors mGlu2 and mGlu3 (encoded by the genes Grm2 and Grm3)." (PMID 25950516, 2015). "MGlu2R gen (GRM2) has been mapped to chromosome 3p21.1–p21.2, and linkage studies of schizophrenia show no positive results regarding this region." (PMID 27242534, 2016). "Although expression of the dimeric form of mGlu3 is reduced in the brains of schizophrenia patients, mGlu2 and mGlu3 are not completely absent, so the Grm2/3-/- mouse cannot be considered a ‘disease model’." (PMID 25950516, 2015). "The observation of reduced and fragmented sleep in Grm2/3-/- mice implies—but does not prove—that abnormal group II metabotropic glutamate receptor signalling may be relevant to sleep disruption in schizophrenia." (PMID 25950516, 2015). "Having said this, it is important to acknowledge that the Grm2/3-/- mouse is not a ‘disease model’ in itself; although there is evidence for the altered dimerisation of mGlu3 in schizophrenia, neither mGlu2 or mGlu3 are completely absent in the brains of schizophrenia patients." (PMID 25950516, 2015).
Anxiety (29 papers, 2008 to 2025). Intense feelings of nervousness, tension, or panic often arise in response to interpersonal stresses. "Grm2, which encodes for the metabotropic glutamate receptor 2, has also been implicated in depression and anxiety." (PMID 38350966, 2024). "Similarly, Grm2 (metatropic glutamate 2 receptor) has been associated with anxiety-like behaviors in several rodent models, and activation of these receptors in the amygdala has been found to be necessary for fear related behaviors." (PMID 30705647, 2018). "Among those, we observed genes that have been associated with PTSD in previous human studies (e.g., DRD2 and HTR2a) or linked to anxiety or PTSD-like behaviors in humans or animal models (Igf2, Grm2, Clock, Trhr)." (PMID 30705647, 2018). "A main aim of the present study therefore was to address this issue by assessing anxiety in the GRM2/3−/− mice." (PMID 25158312, 2015). "Similarly, no consistent differences in anxiety-like behaviours were evident between either GRM2−/− or GRM3−/− mice, and their respective controls." (PMID 25158312, 2015). "Furthermore, the anxiolytic effects of the group II agonists are absent or reduced in single GRM2−/− and GRM3−/− mice, confirming that the drugs are indeed acting through both of the group II metabotropic glutamate receptor subtypes to reduce anxiety." (PMID 25158312, 2015).
depression (26 papers, 2011 to 2025). "As shown by the logistic regression model, testing the simultaneous incidence of DNA methylation changes, depression, and the clustered sociodemographic data on the risk to develop FM, GRM2 DNA methylation and depression were confirmed to increase FM risk." (PMID 34768513, 2021). "Supporting the feasibility of future exploration of Grm3 inhibition in glioma patients, a similar negative allosteric modulator of Grm2/3 (decoglurant) was well tolerated by patients treated in a phase II clinical trial of major depressive disorder (ClinicalTrials.gov: NCT01457677)." (PMID 33575479, 2021).
cognitive deficits (19 papers, 2011 to 2026). "The expression levels of CDK5 and GRM2 were decreased in 5- and 10-month-old 5XFAD mice compared to the controls, providing a mechanistic basis for the synaptic dysfunction and cognitive impairment seen in AD." (PMID 31727875, 2019). "We previously reported that GRM2/3−/− mice exhibit a distinct pattern of cognitive impairments across a range of hippocampus-dependent spatial memory tests." (PMID 25158312, 2015). "First, it is worth noting that where cognitive deficits are apparent in the single lines in this study, they are on appetitively motivated tasks rather than aversively motivated paradigms, as is the case in the GRM2/3−/− mice." (PMID 25158312, 2015).
psychosis (15 papers, 2011 to 2025). "Along the same lines, treatment applications of Grm2/3 negative allosteric modulators for other psychiatric disorders have been suggested based on promising preclinical and preliminary clinical data, including cognitive enhancement, psychotic disorders, and sleep-wake disorders." (PMID 33575479, 2021).
glioma (8 papers, 2013 to 2025). A benign or malignant brain and spinal cord tumor that arises from glial cells (astrocytes, oligodendrocytes, ependymal cells). "Target inhibition in glioma cells was confirmed by a FRET-based cAMP assay where RO1 prevented forskolin-stimulated formation by the Grm2/3 agonist LY-379268." (PMID 33575479, 2021). "Subtypes of GRM2 (mGluR2) are involved in the pathogenesis of diverse cancer types like breast cancer, medulloblastomas and gliomas in such a way that GRM2 is overexpressed in all of these cancers." (PMID 23874428, 2013). "All these results may suggest the essential role of GRM2 in glioma." (PMID 30124166, 2018). "Specially, the present study used real-time PCR to verify the expression of key genes GRM2, GRM7, HTR2A and TFAP2C through human glioma cell line U251." (PMID 30124166, 2018). "In glioblastoma cell culture models, Grm2 and Grm3 gene expression levels were also higher in primary cultures maintained under conditions that retain the GSC phenotype, as compared to long-term glioma cells cultured in serum-containing differentiation medium." (PMID 33575479, 2021).
alcohol dependence (6 papers, 2018 to 2025). Physical and psychological dependence on alcohol. "The role of mGlu2 in alcoholism was further strengthened by two studies in Grm2 mutant rats." (PMID 36980303, 2023). "For alcohol dependence in particular, a reduction of the GRM2 expression (the gene coding for mGlu2) was found in the anterior cingulate cortex (ACC) in patients with AUD as well as in the infralimbic cortex of rats with a history of alcohol dependence." (PMID 36980303, 2023).
autism (6 papers, 2014 to 2024). Persistent deficits in social interaction and communication and interaction as well as a markedly restricted repertoire of activity and interest as well as repetitive patterns of behavior. "Cells in the later pseudotime stage exhibited specific enrichment in synaptic pathways, characterized by the upregulation of several neuronal markers, including CUX2, glutamate metabotropic receptor genes (GRM1, GRM2, and GRM3), and several autism risk genes, including PTEN, SCN2A, and SHANK2." (PMID 39363111, 2024). "For example, we observed a decrease of Grm2, encoding mGluR2, a G-protein-coupled glutamate receptor which interacts with the proline-rich domain of SHANK3 and which has been found decreased in a valproate-induced rat model of autism." (PMID 37008785, 2023).
glioblastoma (5 papers, 2013 to 2024). The most malignant astrocytic tumor (WHO grade IV). "In three of five freshly dissected human glioblastomas, gene expression levels of Grm3 were higher in the CD133-positive GSC population than in CD133-negative non-GSCs, and Grm3 gene expression was overall higher than that of Grm2." (PMID 33575479, 2021).
cocaine addiction (4 papers, 2012 to 2024). "There were 13 genes enriched in cocaine addiction and the circadian entrainment signaling pathway (Bdnf, Gnai1, Gnai3, Grin2d, Grm2, Maob, Cam2, Camk2g, Gng12, Mapk1, Pcb4, Prkm2, and Pdyn)." (PMID 36164400, 2022).
neuroblastoma (4 papers, 2018 to 2024). Neuroblastoma (NB) is the most common solid, extracranial childhood tumor. "It should be noted that GRM2, GRM7 and GRM8 are the mGluR genes that showed the highest expression values in our SK-N-SH cells, which is in accordance with data reported in SH-SY5Y neuroblastoma cells." (PMID 36768378, 2023).
bipolar disorder (2 papers, 2015 to 2024). A disorder of the brain that causes unusual shifts in mood, energy, activity levels and the ability to carry out day-to-day tasks. "Moreover, there is evidence that circadian photosensitivity is elevated in bipolar disorder, just as it is in Grm2/3-/- mice." (PMID 25950516, 2015).
lung adenocarcinoma (1 paper, 2013). A carcinoma that arises from the lung and is characterized by the presence of malignant glandular epithelial cells. "For this reason, we could observe EGFR-like GRM2 over-expression in lung adenocarcinoma." (PMID 23874428, 2013). "Two other important genes i.e. GRM2 and TBXA2R in Merged-module being from the GPCR superfamily, showed over-expression in lung adenocarcinoma." (PMID 23874428, 2013).
mastocytosis (1 paper, 2023). A clonal myeloproliferative neoplasm characterized by the proliferation and accumulation of neoplastic mast cells in one or multiple organs or organ systems. "The results of gene expression profiling indicate the increased expression of genes belonging to the integral component of the membrane in mastocytosis patients (GRM2 and KRTCAP3)." (PMID 37762215, 2023). "Furthermore, increased expression of genes encoding integral membrane components (GRM2 and KRTCAP3) was found in mastocytosis patients." (PMID 37762215, 2023). "Therefore, the increased expression of the GRM2 gene could be investigated for a possible link to neurological and psychiatric symptoms in mastocytosis." (PMID 37762215, 2023). "Significant differences in the expression of the selected genes were found for GRM2 (p = 0.013) and KRTCAP3 (p = 0.036) in mastocytosis patients compared to the heathy controls." (PMID 37762215, 2023).
nematode infection (1 paper, 2019). "Two sub-units of NMDARS, NR2A and NR2B (also known as Grin2A and Grin2B) as well as several AMPARs including the metabotropic glutamate receptors 1 and 2 (mGlu-R1 and mGlu-R2), Gria3, Grm2, Grm4, Grik3 and Grik5 were up-regulated in the pup brain on P7 in response to maternal nematode infection." (PMID 30862816, 2019).
psychosomatic disorders (1 paper, 2025). "This review first outlines how epigenetic dysregulation contributes to psychosomatic disorders through altered expression of genes such as GRM2, TRPA1, SLC6A4, NR3C1, leptin, BDNF, NAT15, HDAC4, PRKCA, RTN1, PRKG1, and HDAC7." (PMID 41439979, 2025).
urinary tract infection (1 paper, 2021). "Indeed, GRM1 and GRM2 can be found in the majority of bacterial species associated with urinary tract infections." (PMID 34054778, 2021).
psychiatric disorder (15 papers, 2008 to 2025). A disorder characterized by behavioral and/or psychological abnormalities, often accompanied by physical symptoms. "The GRM2 gene, which encodes glutamate metabotropic receptor 2, plays an important role in normal brain function, and is a potential target for the development of drugs for neurological and psychiatric diseases." (PMID 36975485, 2023). "Group II metabotropic glutamate receptors (mGluR2 and mGluR3, also called mGlu2 and mGlu3, encoded by GRM2 and GRM3, respectively) are therapeutic targets for several psychiatric disorders." (PMID 18720515, 2008).
infection (12 papers, 2018 to 2026). The state of being infected such as from the introduction of a foreign agent such as serum, vaccine, antigenic substance or organism. "Knockout of Grm2, thus mGluR2, in mice decreased the replication of AIVs in the respiratory tract and improved survival after infection." (PMID 40586559, 2025). "While GRB2 suppression solely would have indicated a regulatory immune response to infection in these settings, the observed GRM2 indicates a more multidimensional effector function of T cells." (PMID 38433833, 2024).
neurological disorders (6 papers, 2013 to 2024). "The study has shown that the GRM2 had huge potential for treating psychiatric and neurological diseases throughout the mammalian central nervous system, and that have been proposed as major targets for the development of drugs for human psychiatric and neurological diseases." (PMID 30124166, 2018).
tumor (6 papers, 2017 to 2025). "The expression of mGluR1 (GRM1) and mGluR5 (GRM5) was conserved from primary tumours to metastatic samples, but moderate changes were evident for other receptors such as mGluR2/3/7/8 (GRM2, GRM3, GRM7, and GRM8)." (PMID 37173906, 2023).
cancer (4 papers, 2013 to 2019). A tumor composed of atypical neoplastic, often pleomorphic cells that invade other tissues. "Given the role of these pathways in cancers, we speculated that GRM1, GRM2 and GRM7 may be associated with DIPG progression by involving in these pathways." (PMID 30124166, 2018).
neurodegenerative disease (4 papers, 2010 to 2025). A disorder of the central nervous system characterized by gradual and progressive loss of neural tissue and neurologic function. "GRM2 modulators have risen in interest, given that allosteric modulators of G-protein-coupled receptors (GPCRs) appear to provide a new strategy to develop novel treatments in neurodegenerative diseases in general and PD in particular." (PMID 35269707, 2022).
GRM2 also shares sentences with these, for which no sentence is quoted: ischemia (7 papers); Alzheimer disease (6); epilepsy (5); Parkinson disease (4); alcoholism (3); autoimmune encephalitis (3); brain disorder (3); cognitive disorder (3); diabetes (3); age (2); anxiety disorder (2); astrocytomas (2); cerebellar ataxia (2); coronavirus disease 2019 (2); Hypertension (2); medulloblastoma (2); melanoma (2); migraine (2); mood disorder (2); post-traumatic stress disorder (2); Rett syndrome (2); acute myeloid leukemia (1); Akinesia (1); alcohol use disorders (1); amnesia (1); asphyxia (1); birth asphyxia (1); brain infarct (1); breast carcinoma (1); central nervous system disorder (1).
A further 34 diseases each share a sentence with GRM2 in 1 paper.